ELK1 (ETS transcription factor ELK1)
Diseases named in the same sentence as ELK1 in open-access papers (continued):
Sharing a sentence is not in itself a finding about the gene and the disease.
melanoma (11 papers, 2015 to 2025). A malignant, usually aggressive tumor composed of atypical, neoplastic melanocytes. "The inhibition of this process via blocking the importins was reported to suppress ELK1’s activation and was found to be the mechanism underlying carvedilol’s melanoma-preventive activity, thus underscoring how this notion could be expanded, and more research should be conducted in this direction." (PMID 40862737, 2025). "Nonetheless, anti-ELK1 expression has been found to be high in Mycosis Fungoides samples as well as in spatial transcriptome profiling of melanoma, which proves the possible relevance of ELK1 in the pathogenesis of CTCL." (PMID 41221277, 2025). "In a 2020 study, ELK1 along with AP-1 and E12 have were credited with the upregulation of key genes in invasive melanoma, correlating its activity with disease progression." (PMID 40862737, 2025). "The gene targets of ELK1 were found to be upregulated in advanced-stage melanoma, correlating its activity to aggressive disease." (PMID 40862737, 2025). "Increased ELK1 activation has also been reported as a consequence of paclitaxel treatment in melanoma cells, due to RAS-RAF-MEK-MAPK pathway activation." (PMID 40862737, 2025). "ELK1 has been reported multiple times in melanoma and has been credited with pro-tumorigenic activity in several models." (PMID 40862737, 2025). "Previously, another group and ours were able to decipher that suppressing the MAPK pathway downregulates HRR gene expression in MAPKi sensitive melanoma cells via the transcription factor ELK1, but the HRR regulation in MAPKi resistant cells remains unknown." (PMID 37674529, 2023). "Our analysis implicates ETS1 and ELK1 in melanoma progression." (PMID 32079144, 2020). "We could show that especially Elk1 is a critical downstream effector mediating increased expression of Rad51 in melanoma cells." (PMID 32719412, 2020). "Indeed, vemurafenib treatment of melanoma cells led to a reduction in c-Myc and Elk1 expression and Elk1 phosphorylation, while Stat3 expression and phosphorylation were not affected." (PMID 32719412, 2020). "In addition, Rad51 expression in melanoma cells was regulated on a transcriptional level by the MAPK signaling pathway with Elk1 as the main downstream transcriptional effector." (PMID 32719412, 2020). "Given that ETS family members are also expressed in immune cells, such as ETS1 in T cells and ELK1 in B cells, we utilized scRNA-seq data to analyze the expression of the PEA3 subfamily, which was found to be associated with immune infiltration, in melanoma cells." (PMID 41502516, 2025). "Finally, ELK1 has also been assessed in the context of carvedilol-mediated melanoma prevention." (PMID 40862737, 2025). "On the functional level, the Elk1 knockdown increased the sensitivity of melanoma cells to the two Rad51i used, B02 and RI-1, most likely due to the double reduction of Rad51 function, on the one hand by Rad51i and on the other hand by the Rad51 deregulation mediated by Elk1." (PMID 32719412, 2020). "In melanoma, several ETS TFs, including FLI1, SPI1, ELF4, ETV7, SPIB, and SPIC, are expressed at higher levels in Cluster A patients, whereas ETV5, ETV4, ELK1, ERF, and ETV2 showed increased expression in Cluster B patients." (PMID 41502516, 2025). "Inhibition of ELK1 activation, by targeting the MAPK pathways in melanoma cells had been explored again in previous studies, in which extracts from Phyllanthus sp." (PMID 40862737, 2025). "Additional inhibition of the MAPK pathway reduced reporter activity to 70% and Elk1 knockdown reduced it to 50%, confirming the role of Elk1 as one of the major transcription factors for RAD51 gene regulation in melanoma cells." (PMID 32719412, 2020).
melanoma (continued). "Network analysis also revealed the potential involvement of three TFs Elk1, AP1, and E12 as the target genes in these networks that were either coordinately upregulated or downregulated in invasive melanoma." (PMID 32079144, 2020). "From this analysis, we have identified Elk1, AP1 and E12 TF networks that coordinately change expression in late melanoma when compared to early melanoma, implicating these TFs in melanoma progression." (PMID 32079144, 2020). "Blockade of BRAF in the BRAFV600E melanoma lines resulted in a drop in activating phosphorylations throughout the MAP Kinase pathway, including the transcription factor ELK1 and downstream kinases p90RSK and MSK1." (PMID 26673621, 2016).
glioblastoma (10 papers, 2012 to 2025). The most malignant astrocytic tumor (WHO grade IV). "AKT3 was associated with glioblastoma; ELK1 participated in neurotrophin TRK receptor signaling pathway and FOXO4 can negatively regulate cell proliferation." (PMID 27903978, 2017). "In glioblastoma, phosphorylated ELK1 is abundant at the GDH1 promoter and activates its transcription, promoting glutamine metabolism." (PMID 34970415, 2021). "ELK1 is a convergence point for signaling pathways downstream of EGFR, including PI3K/Akt, and RNAi knockdown of ELK1 reduces the growth and survival of U138 glioblastoma cells." (PMID 23115635, 2012). "ELK1 is one of the most studied ETS-like transcription factors and has been implicated in several malignancies, including bladder, breast, esophageal cancers and glioblastoma." (PMID 23826213, 2013). "Activation of the ELK1 led to increased survival and proliferation following EGF stimulation in the U138 glioblastoma cells." (PMID 27884160, 2016).
osteosarcoma (10 papers, 2014 to 2025). A usually aggressive malignant bone-forming mesenchymal neoplasm, predominantly affecting adolescents and young adults. "Altogether, the key findings of the present study highlight ELK1/miR-134/PTBP1 signaling cascade as a novel molecular mechanism underlying the acquisition of osteosarcoma chemoresistance." (PMID 33621196, 2021). "ELK1 is known as a major risk factor gene in osteosarcoma progression." (PMID 35123530, 2022). "However, whether ELK1 is regulated by LINC00662/miR-30b-3p axis to be involved in osteosarcoma and its underlying mechanism are still unknown." (PMID 35123530, 2022). "Several recent studies in osteosarcoma focus on how ELK1 regulates the activity of RNA molecules, emphasizing its role as a pro-oncogenic gene silencer." (PMID 40862737, 2025). "In osteosarcoma cells, the ELK1/miR‐134/PTBP1 axis of action promotes resistance to adriamycin in osteosarcoma cells." (PMID 40579921, 2025). "In osteosarcoma, ELK1 was identified in 2003 as a key contributor in immediate-early gene induction by anisomycin and arsenite." (PMID 40862737, 2025). "ELK1 activation was also reported to control anti-apoptotic Bcl-2-related protein A1 (BCL2A1) expression in osteosarcoma cells, in a 2014 study." (PMID 40862737, 2025). "Simultaneously, there were weak negative correlations between the expression of miR-30b-3p and LINC00662/ELK1 in osteosarcoma tissues." (PMID 35123530, 2022). "Our findings indicate that LINC00662 mediates the progression of osteosarcoma via competition with miR-30b-3p to regulate the expression of ELK1." (PMID 35123530, 2022). "LncRNA LINC00662 and ELK1 were significantly increased, while miR-30b-3p was reduced in osteosarcoma tissues." (PMID 35123530, 2022). "The current study indicated that knockdown of LINC00662 repressed cell migration, invasion, and proliferation through sponging miR-30b-3p to regulate the expression of ELK1 in osteosarcoma." (PMID 35123530, 2022). "A previous study demonstrated that ELK1-induced upregulation of MIR100HG promotes the progression of osteosarcoma." (PMID 35123530, 2022). "Meanwhile, we found that the suppressive effects of LINC00662 on the proliferation, migration, and invasion abilities of osteosarcoma cells were reversed by overexpression of ELK1." (PMID 35123530, 2022). "Taken together, significant evidence exists suggesting that ELK1 is able to promote the chemoresistance of osteosarcoma cells to DXR by promoting aerobic glycolysis and cell viability of osteosarcoma cells via upregulation of miR-134-targeted PTBP1." (PMID 33621196, 2021). "In conclusion, the central findings of the current study present evidence indicating that ELK1 promotes the chemoresistance of osteosarcoma cells to DXR via downregulation of miR-134 and upregulation of PTBP1." (PMID 33621196, 2021). "Next, to enhance our understanding of the upstream regulation mechanism of miR-134, differential analysis of GSE12805 was conducted, which revealed that ELK1 was highly expressed in osteosarcoma." (PMID 33621196, 2021). "A notable finding in the present study revealed that ELK1 promoted chemoresistance of osteosarcoma cells to DXR by enhancing aerobic glycolysis and cell viability via inhibition of miR-134 and upregulation of PTBP1." (PMID 33621196, 2021). "Collectively, our findings demonstrated that ELK1 functioned as a facilitator of chemoresistance in osteosarcoma cells by increasing cell viability and proliferation via miR-134 inhibition and upregulation of PTBP1." (PMID 33621196, 2021). "Furthermore, the interactions among LINC00662, miR-30b-3p, and ELK1 in osteosarcoma were also explored." (PMID 35123530, 2022). "This investigation is aimed to verify whether LINC00662 could suppress the progression of osteosarcoma by regulating the miR-30b-3p/ELK1 axis." (PMID 35123530, 2022). "We inferred that sh-LINC00662 may exert anti-tumour role by mediating the miR-30b-3p/ELK1 axis in osteosarcoma." (PMID 35123530, 2022).
osteosarcoma (continued). "We speculated that the LINC00662/miR-30b-3p/ELK1 axis may be involved in the progression of osteosarcoma by regulating these signalling pathways." (PMID 35123530, 2022). "Notably, previous studies have been demonstrated that miR-503-5p or miR-134 can target ELK1 to modulated osteosarcoma progression and chemoresistance." (PMID 35123530, 2022). "Bioinformatics methods and a DLR assay confirmed that LINC00662 could function as a sponge for miR-30b-3p, and ELK1 was the downstream target of miR-30b-3p in osteosarcoma." (PMID 35123530, 2022). "In the present study, we identified ELK1 is a target of miR-30b-3p in osteosarcoma." (PMID 35123530, 2022). "Accumulating evidence has revealed that ELK1, a member of ETS-domain transcription factor family, increases cell growth, differentiation, and survival in tumors, and silencing of ELK1 could suppress cell migration in osteosarcoma cells." (PMID 33621196, 2021). "Previous research has indicated that ELK1 is upregulated in osteosarcoma." (PMID 33621196, 2021). "Thus, the current study aimed to elucidate the role of ELK1/miR-134/PTBP1 signaling cascade in osteosarcoma chemoresistance." (PMID 33621196, 2021). "Recent research has highlighted that ELK1 advances the progression of osteosarcoma." (PMID 33621196, 2021). "ELK1 could promote epithelial to mesenchymal transition (EMT) in osteosarcoma tumor cell and NSCLC." (PMID 34026630, 2021). "ELK1 could promote osteosarcoma progression by the inactivating Hippo pathway." (PMID 31537905, 2020). "In the present study, the expression levels of LINC00662, miR-30b-3p, and ELK1, as well as the effects of LINC00662 and miR-30b-3p on the malignant behaviour of osteosarcoma cells were determined." (PMID 35123530, 2022). "Future studies are required to fully clarify the specific mechanisms by which ELK1 combined with miR-134 and PTBP1 influence chemoresistance to DXR treatment in osteosarcoma." (PMID 33621196, 2021). "Initially, the data obtained during the present study demonstrated that ELK1 and PTBP1 were highly expressed while miR-134 was poorly expressed in osteosarcoma tissues and cell lines." (PMID 33621196, 2021). "In osteosarcoma, Cyr61 promotes EMT and the metastasis of tumor cells through the Raf-1/MEK/ERK/Elk-1/TWIST-1 signaling pathway." (PMID 34970415, 2021). "Tumor-derived CXCL5 can promote human CRC metastasis by activating ERK/Elk-1/Snail and AKT/GSK3β/β-catenin pathway, accelerate osteosarcoma growth and can serve as a biomarker for non-small cell carcinoma, etc.." (PMID 33240582, 2020). "Our results indicate that Cyr61 promotes the EMT of osteosarcoma cells by regulating EMT markers via a signal transduction pathway that involves αvβ5 integrin, Raf-1, MEK, ERK, and Elk-1." (PMID 25326651, 2014). "Finally, a direct link between miR-30b-3p and ELK1 was identified, proposing a new regulatory axis that involves LINC00662/miR-30b-3p/ELK1 with a pro-tumorigenic role in osteosarcoma progression." (PMID 40862737, 2025). "Rescue experiments suggested that ELK1 overexpression and downregulation of miR-30b-3p reversed the suppressive effects of sh-LINC00662 on the cell migration, invasion, and proliferation in osteosarcoma." (PMID 35123530, 2022). "In this study, we revealed that ELK1 was significantly increased in osteosarcoma tissues and cells, but the function of ELK1 was not explored." (PMID 35123530, 2022). "Thus, our study set out to investigate the role of ELK1 regulating miR-134 and PTBP1 in chemoresistance to osteosarcoma cells." (PMID 33621196, 2021). "Moreover, the results of Pearson’s correlation analysis showed that there was a weak negative correlation between miR-30b-3p and ELK1 in osteosarcoma tissues." (PMID 35123530, 2022).
osteosarcoma (continued). "In addition, Cyr61-promoted EMT is mediated by αvβ5 integrin, Raf-1, mitogen-activated protein kinase kinase (MEK), extracellular signal-regulated kinase (ERK), and Elk-1 signaling pathways, and may be involved in the regulation of EMT in osteosarcoma." (PMID 25326651, 2014).
Alzheimer disease (9 papers, 2010 to 2025). A progressive, neurodegenerative disease characterized by loss of function and death of nerve cells in several areas of the brain leading to loss of cognitive function such as memory and language. "ELK1 has been previously shown to initiate regionalized neuronal death and to associate with inclusions present in Alzheimer’s disease, Lewy body disease, and Huntington’s disease." (PMID 37789374, 2023). "In sum, these experiments show that T417+ Elk-1 specifically associates with neuronal inclusions characteristic of Alzheimer's Disease." (PMID 20126313, 2010). "Furthermore, we find that T417+ Elk-1 uniquely associates with several types of inclusions present in cases of human Lewy body Disease, Alzheimer's disease, and Huntington's Disease." (PMID 20126313, 2010). "We tested for remarkable Elk-1 and/or pElk-1 protein in the classic brain regions undergoing clinically significant neuronal loss in either human Lewy Body disease (e.g. Parkinson's Disease), Alzheimer's disease (AD), or Huntington's Disease (HD)." (PMID 20126313, 2010). "Given this novel regionalized function, we assessed whether extranuclear Elk-1 and/or phospho-Elk-1 (pElk-1) protein might be associated with a spectrum of human neurodegenerative disease cases including Lewy body Disease (e.g. Parkinson's), Alzheimer's disease, and Huntington's Disease." (PMID 20126313, 2010). "Researchers found that ELK1 levels are higher in patients with Alzheimer’s disease and animal models." (PMID 40307574, 2025). "Since patients with AUD often experience alcoholic dementia and cognitive decline, there have been studies on the role of Elk-1 in Alzheimer’s disease and long-term memory." (PMID 37146054, 2023). "Previous studies have shown that ELK1 phosphorylation can be modulated in various central nervous system diseases (CNS diseases), such as Alzheimer’s’ disease, Huntington’s disease, Down syndrome and depression." (PMID 29780667, 2018). "Elk-1 is a transcription factor that directly regulates the expression of immediate early genes and is crucially involved in long-term memory, drug addiction, Alzheimer’s disease, Down’s syndrome, breast cancer, and depression." (PMID 37146054, 2023). "This suggests that targeting ELK1 could be a potential treatment strategy for Alzheimer’s disease." (PMID 40307574, 2025). "Finally, in Alzheimer's Disease, where the staining is more intense then the canonical AT8 staining, T417+ Elk-1 may serve as an early biomarker for neurodegenerative processes." (PMID 20126313, 2010).
Huntington disease (8 papers, 2010 to 2025). Huntington disease (HD) is a rare neurodegenerative disorder of the central nervous system characterized by unwanted choreatic movements, behavioral and psychiatric disturbances and dementia. "For instance, ELK1 has been implicated in early epigenetic changes and neuroprotection in cellular models of Huntington’s disease." (PMID 35370543, 2022). "More importantly, both ELK1 and its phosphorylated form (p-ELK1) might be linked to several human neurodegenerative diseases, including Parkinson’s disease, Huntington’s disease and AD42." (PMID 40307574, 2025). "Interestingly, a neurotoxic form of ELK1 is associated with the development of neuronal inclusions in several neurodegenerative disorders including Lewy body, Alzheimer’s, and Huntington’s diseases." (PMID 35370543, 2022). "Finally, we assessed whether T417+ Elk-1 could associate with inclusions present in human Huntington's Disease tissue." (PMID 20126313, 2010). "The fact that a subset of inclusions from Parkinson's Disease and Huntington's Disease show colocalization with T417+ Elk-1 likely reflect both disease and detection processes." (PMID 20126313, 2010).
atherosclerosis (6 papers, 2010 to 2023). A disease characterized by the build-up of fatty material and calcium deposition in the arterial wall resulting in partial or complete occlusion of the arterial lumen. "High fat/atherogenic diet containing high cholesterol and cholic acid induces endothelial dysfunction, atherosclerosis and increases oxidative stress by increasing the expression of oxidation-sensitive genes such as Elk-1 and p-CREB." (PMID 24370063, 2013). "High cholesterol diet induces endothelial dysfunction, atherosclerosis and increases oxidative stress by increasing the expression of oxidation-sensitive genes, such as Elk-1 and p-CREB." (PMID 20727145, 2010). "ELK1 is related to inflammatory response, endothelial dysfunction and atherosclerosis in IS." (PMID 37794518, 2023).